BIRC5 (baculoviral IAP repeat containing 5)
Diseases named in the same sentence as BIRC5 in open-access papers (continued):
Sharing a sentence is not in itself a finding about the gene and the disease.
breast carcinoma (continued). "Bioinformatics analysis of publicly available data from the TCGA database confirmed statistically significant higher levels of BIRC2 (p = 0.0213), BIRC3 (p = 0.0029), BIRC5 (p = 0.0040) gene expression in breast cancer patients under 51 years of age." (PMID 33673050, 2021). "While breast cancer patients with lower level of BIRC5 showed longer relapse-free survival and better overall survival, patients with increased BIRC5 expression displayed shorter distant metastasis-free survival." (PMID 32043523, 2020). "First, our analysis using the Oncomine and TCGA databases revealed that BIRC5 gene was higher expressed in breast cancer patients with respect to normal individuals." (PMID 32043523, 2020). "It is interesting to note that BIRC5 is one of the genes of the PAM50 signature (an intrinsic breast cancer subtype classifier), and that high expression of this gene is one of the defining features of basal-like tumors, as defined by this approach." (PMID 32183150, 2020). "In terms of breast cancer, BIRC5 was highly expressed in triple-negative subtype and BIRC5 repression was able to decrease the proliferation of breast cancer cells, implying that BIRC5 acts like a tumor driver." (PMID 32043523, 2020). "BIRC5 co-expression profile consists of a large cluster of 19574 genes from 336 breast cancer samples." (PMID 32043523, 2020). "Oncomine database revealed that BIRC5 was significantly higher expressed in breast cancer patients compared with the matched normal individuals." (PMID 32043523, 2020). "TCGA data analyzed by the Ualcan online tool confirmed that higher BIRC5 was expressed in breast cancer tissues than in normal tissues (P<0.05)." (PMID 32043523, 2020). "The present study validated that BIRC5 was overexpressed in breast cancer patients and was responsible for a worse survival." (PMID 32043523, 2020). "Recently, the CDC20 and BIRC5 small interfering RNAs delivered by additive polyplexes displayed novel therapy efficacy in breast cancer cell." (PMID 32043523, 2020). "BIRC5 is overexpressed in various tumors and has been found as a prognostic marker in gastric cancer, renal cell carcinoma, and breast cancer." (PMID 32974146, 2020). "Pearson correlation analysis was performed to assess the relationships between EGFR and BIRC5 expression and clinical characteristics of breast cancer patients using the 855-patient dataset." (PMID 32001757, 2020). "Interrogation of CCLE database revealed a positive correlation of FZD5 with FOXM1, BRCA1, and BIRC5, several key factors related to cell cycle, DNA replication, DNA damage repair, and survival, in a total of 57 breast cancer cell lines." (PMID 33311446, 2020). "Further large-scale studies are needed to more precisely confirm the value of BIRC5 in treatment of breast cancer." (PMID 32043523, 2020). "Further large-scale studies are needed to more precisely confirm the prognostic significance of BIRC5 in breast cancer treatment." (PMID 32043523, 2020). "After checking the DNA methylation status in TCGA, we found that BIRC5 expression was negatively related to DNA methylation and higher promoter methylation level of BIRC5 was expressed in breast cancer tissues." (PMID 32043523, 2020). "In a variety of human cancers, such as breast cancer, pancreatic cancer, hepatocarcinoma, neuroblastoma, and esophageal carcinoma, high expression of BIRC5 indicated poor clinical outcomes." (PMID 31093306, 2019). "BIRC5 has been reported to be selectively expressed in most tumors, including breast carcinomas, and yet low in adult tissues." (PMID 31579605, 2019). "Initially, overexpression of BIRC5 in canine mammary tumour (CMT) tissues was confirmed by real-time PCR." (PMID 31530877, 2019).
breast carcinoma (continued). "This is consistent with our results here that BIRC5 as one of the most up-regulated genes in breast cancers." (PMID 29268695, 2017). "Several of these genes have been previously linked to tumourigenesis in breast cancer, including KDM5B, RAD21, BIRC5, AURKA and MSRA." (PMID 27341628, 2016). "We found that BIRC5 was expressed significantly higher in invasive breast carcinoma compared to normal breast tissues (p = 5.5e-31) and increased with breast cancer stage (p < 0.00001)." (PMID 25763854, 2015). "In advanced metastatic prostate cancer, miR-203 targets BIRC5, whereas in breast cancer metastasis it targets SNAI2." (PMID 25284788, 2014). "Known breast cancer susceptibility genes like TPX2, AURKA, TK1 and BIRC5 are among the top 7 global drivers (the other 3 top drivers are GINS2, COX4NB and NUP93)." (PMID 21806811, 2011). "It has been claimed that BIRC5 has the potential to be a prognostic marker in breast cancer patients." (PMID 20051122, 2010). "BIRC5 is known to be an Inhibitor of Apoptosis (IAP) that is over expressed in numerous human cancers including breast cancer." (PMID 20051122, 2010). "Finally, the differential expression of the BIRC5 gene in breast cancer tissue was analyzed using the bioinformatics tool Gene Expression Profiling Interactive Analysis (GEPIA)." (PMID 40725442, 2025). "Notably, the current study reveals a new role of Nuclear Protein 1 (NUPR1/P8/COM1) in regulating the expression of HDAC5, ERBB2 (and the survival reliance switch from estrogen to EGF) and BIRC5 (a well-known oncogene) in breast cancer cells." (PMID 39991577, 2025). "The possible biological explanation for the association between the rs9904341 G>C variant and breast cancer susceptibility lies in its location at the cell cycle-dependent element (CDE) binding site and cell cycle homology regions (CHR) of the BIRC5 gene promoter." (PMID 40725442, 2025). "Notably, BIRC5 expression varies significantly by breast cancer subtype, with the highest expression in triple-negative cases." (PMID 41373575, 2025). "We also found that AURKB, BIRC5, CDCA8, and FOXM1 are all part of the meta-PCNA proliferation gene signature, and high levels of expression of genes in this signature are associated with poor prognosis in breast cancer." (PMID 39335162, 2024). "Furthermore, in researches of patients with breast cancer, lymphoid leukemia and melanoma, BIRC5 can be recognized by cytotoxic T lymphocytes and generate immune response." (PMID 38556560, 2024). "BIRC5 (Survivin) has been reported to be an important biomarker for breast cancer, with high expression of BIRC5 correlated with worse survival, and is a promising target for drug discovery and breast cancer therapeutics." (PMID 37193964, 2023). "Furthermore, BIRC5 holds promise as a prospective candidate for identifying and predicting biomarkers for the identification, assessment, or prediction of breast cancer in patients." (PMID 37895143, 2023). "BIRC5: BIRC5 may be adopted as a promising predictive marker and potential therapeutic target in breast cancer." (PMID 37468832, 2023). "A recent study based on TCGA dataset and hospital data showed that BIRC5 was highly expressed in breast cancer tissues compared with normal individuals and may be adopted as a promising therapeutic bio-target." (PMID 35461228, 2022). "BIRC5 is a molecular marker of the poor prognosis in lung, pancreatic, and breast cancers." (PMID 35406376, 2022). "This suggests that the BIRC5 protein is upregulated in breast carcinomas." (PMID 36358602, 2022).
breast carcinoma (continued). "DNA amplification in the BIRC5 gene was found in 15/229 (0.066%) breast cancer samples." (PMID 35331169, 2022). "It has been shown that BIRC5 is highly expressed in breast cancer, and its expression is correlated with relapse-free survival and overall survival; it, therefore, may have potential as a useful predictive marker and therapeutic target in this context." (PMID 35309512, 2022). "A recent study confirmed that BIRC5 could act as a reliable prognostic indicator in breast cancer patients, but the expression, clinical significance, and its impact on the immune microenvironment remain largely unclear in low-grade glioma." (PMID 35309512, 2022). "It has been reported that BIRC5 was overexpression in more than half of breast cancer patients." (PMID 34712656, 2021). "Notably, BIRC5 has been explored as one of the hub ATGs in the prognostic signatures of breast cancer, prostate cancer, and human endometrial cancer, as well as GRID2 in gastric cancer and endometrial carcinoma." (PMID 34746127, 2021). "BIRC5 vaccines for cancer immunotherapy have successfully passed proof-of-concept and have already been applied in clinical trials to treat malignant glioblastoma, ovarian cancer, breast cancer, colon cancer, lung cancer, and the like." (PMID 33477943, 2021). "In this study we asked if we could get clinically helpful information on how active BIRC5 is in breast cancer patients?" (PMID 34064473, 2021). "Moreover, there have been reported direct interactions of E2F1 and retinoblastoma protein (RB) with the promoter of RECQL4 in prostate cancer cells and RECQL4 with BIRC5 in breast cancer cells." (PMID 33541355, 2021). "Next, we checked the prognostic significance of BIRC5 in breast cancer and demonstrated that high BIRC5 expression was responsible for shorter relapse-free survival, worse overall survival, reduced distant metastasis-free survival, and increased risk of metastatic relapse event." (PMID 32043523, 2020). "However, the detailed expression pattern, potential function, prognostic value, and drug interaction network of BIRC5 remain largely unclear in breast cancer." (PMID 32043523, 2020). "Besides, higher promoter methylation level of BIRC5 was observed in breast cancer tissues, with respect to normal tissues." (PMID 32043523, 2020). "Additionally, BUB1 and BIRC5 have been linked to stemness, where depletion of BUB1 reduced cancer stem cell potential in MDA-MB-231 and MCF-7 breast cancer cell lines and BIRC5 is commonly expressed in embryonic tissues and cancer but not in adult tissues." (PMID 32457901, 2020). "Indeed, several studies have reported BIRC5 as a prognostic marker in breast cancer through experimental evidences." (PMID 32043523, 2020). "Given that high level of BIRC5 conferred shorter survival in breast cancer patients, we then sought to investigate whether BIRC5 and potential chemical drugs could modulate each other using the Comparative Toxicogenomics Database." (PMID 32043523, 2020). "Second, we investigated the mechanisms of BIRC5 dysregulation in breast cancer." (PMID 32043523, 2020). "Therefore, the present work was carried out to validate the expression pattern, potential function, prognostic value, and drug interaction network of BIRC5 in breast cancer by performing bioinformatics analysis of several large online databases." (PMID 32043523, 2020). "Quantitative analysis of transcript abundance among the three sub-populations of OR genes confirmed that the genes associated with breast cancer cell proliferation (MKI67, AURKA, BIRC5, CCNB1, MYBL2) were significantly abundant in sub-population I with OR2B6 upregulation." (PMID 31551495, 2019). "Serum BIRC5 levels in different cases of human breast cancer has been quantitated using ELISA44." (PMID 31530877, 2019).
breast carcinoma (continued). "At the clinical level, retrospective Kaplan–Meier analysis of expression cohorts of breast tumor showed that high survivin (BIRC5) expression levels significantly (p-value < 0.0001) correlate with poor relapse-free survival (HR = 1.98) in endocrine therapy-treated ER+ breast cancer patients." (PMID 29326587, 2017). "Moreover, BIRC5 was expressed significantly higher in triple-negative breast cancer, a type of breast cancer known to be more aggressive and with poor prognosis, compared to all other combined subtypes (p = 3.5e-8)." (PMID 25763854, 2015). "Moreover, enhanced IRF1 expression in breast cancer cells down-regulates the inhibitor of apoptosis protein, survivin (BIRC5)." (PMID 22295238, 2011). "The gene BIRC5 on 17q25.3, which encodes the apoptosis inhibitor survivin, co-amplifies with ERBB2 and correlates with high histological grade and a poor prognosis in breast cancer when overexpressed." (PMID 20158880, 2010). "EBV oncogene LMP1 in NPC, PTGS2 in endometrial carcinoma and MYC in breast cancer may induce the BIRC5 expression by different pathways." (PMID 18570662, 2008). "Interrupting the ERBB2-ERBB3 heterodimer using lapatinib (GW572016, GlaxoSmithKline), a potent small-molecule inhibitor of EGFR and ERBB2 tyrosine kinases, leads to proteasomal degradation of BIRC5 and induces apoptosis both in breast cancer cell lines overexpressing ERBB2 and in primary tumors." (PMID 19007432, 2008). "Furthermore, PTPRT was negatively correlated with BIRC5 in other cancer types such as breast carcinoma (BRCA, R = -0.497, P < 0.0001), pancreatic adenocarcinoma (PAAD, R = -0.371, P < 0.0001), stomach adenocarcinoma (STAD, R = -0.279, P < 0.0001), and mesothelioma (MESO, R = -0.465, P < 0.001)." (PMID 38216925, 2024). "Moreover, the expression of BIRC5 in bodily fluids may serve as a highly effective marker for the early detection and diagnosis of breast cancers." (PMID 36358602, 2022). "Therefore, the BIRC5 gene and survivin may be an effective therapeutic target for breast cancer, including TNBC." (PMID 33673050, 2021). "Finally, baculoviral inhibitor of apoptosis repeat-containing 5 (BIRC5) is an inhibitor of apoptosis that is always absent in normal tissues and is associated with various cancers, such as breast cancer and OC." (PMID 31987036, 2020). "Since patients with ER or PR negative, HER-2 positive, basal-like or triple-negative status generally display therapy insensitivity and inferior prognosis, our results suggested that lower expression of BIRC5 may predict a satisfied clinical outcome of breast cancer." (PMID 32043523, 2020). "Thus, our findings provided evidence that BIRC5 could be a useful predictive prognostic marker for breast cancer." (PMID 32043523, 2020). "(2015) showed that FOXM1 could target BIRC5 to modulate breast cancer survival and chemoresistance." (PMID 31579605, 2019). "Thus, various roles of survivin in chemotherapy resistance may contribute to the prognostic significance of BIRC5 gain in the present series of patients with HR+ and HR- breast cancers." (PMID 23679233, 2013). "Boxplot analyses revealed that MELK, BIRC5, and CEACAM6 were significantly overexpressed in HR+/HER2– breast cancer tissues compared to normal breast tissues in the TCGA cohort, whereas RARRES1 expression was markedly reduced in tumor tissues (p < 0.001)." (PMID 40936892, 2025). "In the presence of the three variants associated with BIRC5 (rs8073069, rs17878467, and rs9904341), tobacco and alcohol consumption were not statistically significant, suggesting that these variables do not increase the risk or susceptibility to developing breast cancer (BC)." (PMID 40725442, 2025). "We also showed that Tamoxifen downregulates the expression of BIRC5 and increases the conversion of LC3B-II in MCF7 and ZR-75-1 (ER+ breast cancer) cells." (PMID 39991577, 2025).
breast carcinoma (continued). "The metastasis-related gene MMP11 and proliferation-related genes BIRC5, MYBL2, MKI67 (Ki67), AURKA (STK15), CCNB1, and ERBB2 (HER2) from the Oncotype DX gene set exhibit significant up-regulation in tumor samples of breast cancer (BRCA)." (PMID 38254834, 2024). "In breast cancer datasets, we found significant upregulation of both centrosome clustering proteins KIFC1, AURKB, BIRC5, and CDCA8 and the oncogenes FOXM1, ATAD2, and E2F1 in tumor samples compared to normal samples." (PMID 39335162, 2024). "In breast cancers, we found significant upregulation of KIFC1, AURKB, BIRC5, and CDCA8 in tumor samples of both the GEPIA and UALCAN datasets, compared to normal samples." (PMID 39335162, 2024). "BIRC5/Survivin is an inhibitor of apoptosis protein (IAP) and is overexpressed in a wide spectrum of tumors, including breast cancer." (PMID 34371830, 2021). "Trastuzumab, which is primarily used in breast cancer, interacts via the PI3K pathway with BIRC5 and shows some effectiveness." (PMID 33917186, 2021). "FOXM1 overexpressing breast cancer cells displayed an anti-apoptotic phenotype due to up-regulated expression of XIAP and BIRC5 anti-apoptotic genes." (PMID 33431968, 2021). "Another eight ARGs (BCL2, BIRC5, EIF4EBP1, ERO1L, FOS, GAPDH, ITPR1, and VEGFA) were explored, and the author found that these genes not only were significantly associated with overall survival but also could predict distant metastasis-free survival in breast cancer." (PMID 34869345, 2021). "Analyses using an 855-patient breast cancer gene expression dataset identified that both EGFR and BIRC5 have significantly higher expression levels in basal-like patient tumors compared to those of other subtypes." (PMID 32001757, 2020). "Recently, on the basis of the GEO database, Gu and his colleagues constructed an ARG model consisting of eight genes (BCL2, BIRC5, EIF4EBP1, ERO1L, FOS, GAPDH, ITPR1, and VEGFA), which can be used as an independent prognostic indicator of breast cancer." (PMID 32649310, 2020). "Amongst the other highly significant upregulated CR genes by p-value and log2FC, SKA2, MKI67, HJURP, BIRC5, and CCNB1 are upregulated in breast cancer tissues and all five except for SKA2 have been identified as prognostic markers for breast cancer." (PMID 32457901, 2020). "However, the prognostic significance of BIRC5 remains unclear in breast cancer." (PMID 32043523, 2020). "Breast cancer patients with more advanced Scarff–Bloom–Richardson (SBR) grade and Nottingham Prognostic Index (NPI) showed elevated BIRC5 gene." (PMID 32043523, 2020). "Consistently, BIRC5, E2F2, FOXM, and MCM5, showed higher expression in breast cancer tissues than in normal tissues, according to the immunohistochemical assessment from HPA database." (PMID 31579605, 2019). "BIRC5 and FOXM1 downregulation and IL24 induction was also evident in breast cancer patient datasets following taxane treatment." (PMID 28187446, 2017). "In mouse mammary carcinoma (BA) xenografts, porfimer-PDT led to an increase in HIF-1α, BIRC5, and VEGF protein levels." (PMID 26657503, 2016). "While RAD21, BIRC5 and AURKA have already been recognised as important players in luminal breast cancers progression process, the remaining genes represent novel biomarkers and targets to explore." (PMID 27341628, 2016). "Our data suggest that, in breast cancer cells, YAP1/β-catenin complex with TBX3, which phenocopies TBX5 at BCL2L1 and BIRC5 but additionally promotes cMYC expression, potentially by combining known TEAD- and TBX3-binding elements." (PMID 26549256, 2015). "On the other hand, 5 genes were differentially expressed with significant difference between the breast cancer patients and carriers, BRCA1 (p = 0.03), BIRC5 (p = 0.035), CCND2 (p0.034), ATM (p = 0.012) and IGF1R (p = 0.025)." (PMID 25403427, 2014). "We also detected BIRC5 and LASP1 expression at mRNA level in breast cancer cell lines and MCF-10A cell line." (PMID 22713668, 2012).